KIR3DP1 (killer cell immunoglobulin like receptor, three Ig domains pseudogene 1)
Synonyms: KIRX; KIR48; KIR2DS6; KIR3DS2P; CD158C
Gene: Transcribed unprocessed pseudogene on chromosome 19 (54,786,355 to 54,790,318, forward strand). Ensembl gene ENSG00000264257.
Diseases named in the same sentence as KIR3DP1 in open-access papers:
KIR3DP1 is named in the same sentence as 2 diseases in open-access papers, as found by Europe PMC text mining. Sharing a sentence is not in itself a finding about the gene and the disease. The quoted sentences say what the papers report.
Alzheimer disease (1 paper, 2021). A progressive, neurodegenerative disease characterized by loss of function and death of nerve cells in several areas of the brain leading to loss of cognitive function such as memory and language. "Killer inhibitory receptors similar to KIR222 and KIR3DP1 that may function in cell clearance were associated with Alzheimer’s disease." (PMID 34182925, 2021).
KIR3DP1 also shares sentences with these, for which no sentence is quoted: Diabetes (1 paper).